MIR20A (microRNA 20a)
Synonyms: hsa-mir-20; hsa-mir-20a; C13orf25; MIR20; MIRH1; MIRHG1; MIRN20; MIRN20A; miR-20; miRNA20A; mir-20a
Gene: MicroRNA gene on chromosome 13 (91,351,065 to 91,351,135, forward strand). Ensembl gene ENSG00000283762.
Gene Ontology:
Biological process: miRNA-mediated post-transcriptional gene silencing
Cellular component: RISC complex
Homologues: Orthologues: chimpanzee ptr-mir-20a (100% identical), pig MIR20A (100% identical), guinea pig MIR20A (99% identical), mouse Mir20a (94% identical), rat Mir20a (93% identical), tropical clawed frog xtr-mir-20a (86% identical), dog MIR20A (82% identical), zebrafish mir20b (73% identical), zebrafish dre-mir-20a (34% identical). Paralogues in human: MIR20B (76% identical), MIR106B (63% identical), MIR17 (63% identical), MIR18A (55% identical).
Diseases named in the same sentence as MIR20A in open-access papers:
MIR20A is named in the same sentence as 6 diseases in open-access papers, as found by Europe PMC text mining. Sharing a sentence is not in itself a finding about the gene and the disease. The quoted sentences say what the papers report.
tumor (2 papers, 2021 to 2025). "miRNAs such as Mir155, Mir181, Mir92a, and Mir20a have been implicated in sustaining a tumor-promoting inflammatory milieu, with roles in immune regulation, macrophage polarization, and modulation of chemokine expression." (PMID 40869212, 2025).
MIR20A also shares sentences with these, for which no sentence is quoted: cancer (1 paper); colon cancer (1); gastric cancer (1); lung carcinoma (1); pancreatic adenocarcinoma (1).